IL6R (interleukin 6 receptor)
Diseases named in the same sentence as IL6R in open-access papers (continued):
Sharing a sentence is not in itself a finding about the gene and the disease.
Retinal atrophy (1 paper, 2017). A nonspecific term denoting wasting, especially as a result of degeneration, of the retinal pigment epithelium (RPE) and neurosensory retinal cells. "None of the IL6 perturbations (IL6 KO, injection of anti-IL6Rα antibody or anti-gp130 antibody) caused retinal atrophy in the area of detachment (data of retinal thickness not shown)." (PMID 28645275, 2017).
retroperitoneal fibrosis (1 paper, 2020). "IL-6 and IL-6R expression in the tissue lesions of IgG4-related retroperitoneal fibrosis and IgG4-related sialadenitis patients were also significantly higher than that in the normal tissues." (PMID 32733444, 2020).
seborrheic dermatitis (1 paper, 2024). A chronic, inflammatory skin disorder that affects the scalp, central face and skin folds; it is characterized by scaling and itching. "IL6R was associated with seborrheic dermatitis and difficulty walking with increased odds in AFR and reduced odds in EUR." (PMID 38580710, 2024).
sialadenitis (1 paper, 2020). Sialadenitis is an infection of the salivary glands. "The immunochemical analysis of the retroperitoneum tissue revealed higher IL-6 and IL-6R expression in both the tissue of IgG4-related RPF and IgG4-related sialadenitis than in the control tissue." (PMID 32733444, 2020). "Interestingly, we have found remarkably higher levels of IL-6 and IL-6R expression in both the IgG4-related RPF and IgG4-related sialadenitis tissues." (PMID 32733444, 2020).
social phobia (1 paper, 2023). An anxiety disorder characterized by an intense, irrational fear of one or more social or performance situations in which the individual believes that he or she will be scrutinized by others. "We also observed statistically significant associations between SOD2 rs4880 and obsessive–compulsive symptoms, PON1 rs705381 and social phobia, IL1B rs1071676 and AUDIT scores, and IL6R rs2228145 and compulsions in alcohol-addicted patients." (PMID 38275640, 2023).
spinal cord injury (1 paper, 2012). Penetrating and non-penetrating injuries to the spinal cord resulting from traumatic external forces (e.g., WOUNDS, GUNSHOT; WHIPLASH INJURIES; etc.). "The objective of this study was to clarify the effects of a temporal blockade of IL-6/IL-6 receptor (IL-6R) engagement, using an anti-mouse IL-6R monoclonal antibody (MR16-1), on macrophage activation and the inflammatory response in the acute phase after spinal cord injury (SCI) in mice." (PMID 22369693, 2012).
status epilepticus (1 paper, 2013). Status epilepticus is defined as a continuous seizure lasting more than 30 min, or two or more seizures without full recovery of consciousness between any of them. "The upregulation of both IL6 and IL6R occurs following status epilepticus." (PMID 24146813, 2013).
steatosis (1 paper, 2019). Increased lipid within the cytoplasm of cells. "IL-6-deficient mice display a milder NAFLD severity and antibody mediated IL-6 receptor (IL-6R) neutralization improved liver damage in mice fed methionine choline deficient (MCD) diet, despite enhanced steatosis." (PMID 31921154, 2019).
Streptococcus pneumoniae pneumonia (1 paper, 2024). "We show that a heightened risk of Streptococcus pneumoniae pneumonia in CHIP carriers was abrogated in individuals with this hypomorphic IL6R SNP (in those with low genetic IL6R)." (PMID 38573824, 2024).
subarachnoid hemorrhage (1 paper, 2024). A serious neurological disorder characterized by intracranial hemorrhage into the subarachnoid space. "This study investigated the effects of treating the inflammatory response and cerebral vasospasm after subarachnoid hemorrhage with the interleukin-1 receptor antagonist anakinra and the interleukin-6 receptor antagonist tocilizumab." (PMID 39768906, 2024).
systemic mastocytosis (1 paper, 2025). Systemic mastocytosis (SM) comprises a heterogeneous group of rare acquired and chronic hematological malignancies that are related to an abnormal proliferation of mast cells in tissue, including bone marrow, with or without skin involvement. "Indeed, additional germline variants in KIT and in genes encoding for cytokines or their receptors (e.g., IL13, IL6, IL6R, IL31, IL4R), as well as increased copy numbers of the TPSAB1 gene encoding for α‐tryptase, have been increasingly recognized as associated with systemic mastocytosis in adults." (PMID 41177946, 2025).
teratocarcinoma (1 paper, 2022). A germ cell tumor characterized by the presence of an embryonal carcinoma component and a teratoma component. "IL-6R was identified as a direct target of miR-let-7a, and the miR-let-7a inhibitor significantly increased the level of IL-6R expression, resulting in increased proliferation, reduced apoptosis, and inhibited inflammatory response in ATDC5 cells, which are derived from mouse teratocarcinoma." (PMID 36612019, 2022).
tuberculoid leprosy (1 paper, 2016). A principal or polar form of leprosy in which the skin lesions are few and are sharply demarcated. "Our previous studies on stable tuberculoid leprosy had indicated that IL-23 and IL23R but not IL-6 and its receptor (IL-6R) were associated with Th17 cell differentiation." (PMID 27035913, 2016).
uterine cancer (1 paper, 2021). Primary or metastatic malignant neoplasm involving the uterine corpus and/or the cervix. "Furthermore, bladder, cervical, endometrioid, and uterine cancers, displayed IL6 upregulation and both IL6R and IL6ST downregulation." (PMID 34576335, 2021).
ventricular tachycardia (1 paper, 2025). A disorder characterized by an electrocardiographic finding of three or more consecutive complexes of ventricular origin with a rate greater than a certain threshold (100 or 120 beats per minute are commonly used). "Indeed, mice that underwent thoracotomy did not exhibit greater ventricular tachycardia inducibility compared with sham mice, consistent with the lack of macrophage-dependent IL-6Rα production and subsequent IL-6 transsignaling." (PMID 40048254, 2025).
Ventriculomegaly (1 paper, 2015). An increase in size of the ventricular system of the brain. "ISSI alone (IL-6R), was associated with significantly lower risk of ventriculomegaly." (PMID 25793991, 2015).
vitiligo (1 paper, 2024). Generalized well circumscribed patches of leukoderma that are generally distributed over symmetric body locations and is due to autoimmune destruction of melanocytes. "Tocilizumab therapy has been found to increase serum IL-6 levels following IL-6R blockage; this increase could potentially have systemic effects, such as exacerbating vitiligo by intensifying the imbalance between Tregs and Th17 cells." (PMID 39201060, 2024).
xerostomia (1 paper, 2022). Dryness of the mouth resulting from reduced salivary secretion. "The PPI network genes IL6R, EGFR, NFKB1, MPO, and TNFSF13B constitute a possible biomarker signature of xerostomia." (PMID 35268532, 2022). "The IL6R, EGFR, NFKB1, MPO, and TNFSF13B genes might all have implications in the diagnosis and intervention of xerostomia." (PMID 35268532, 2022).
ZIKV infection (1 paper, 2022). "The downregulation of inflammatory genes CCL18, CCL19, CXCL6, CXCL9, IL6R, IL11, IL24, and Integrin Subunit Beta 3 (ITGB3) with ZIKV infection may reflect placental immune tolerance." (PMID 35304593, 2022).
tumor (385 papers, 2007 to 2026). "The overexpression of circNFIX is implicated in tumor malignancy by up-regulating the expression of the miR-647 target gene interleukin-6 receptor (IL-6R) and activating the downstream JAK1/STAT3 signaling pathway." (PMID 39904996, 2025). "Tumor-associated OC endothelial cells within the OC-TME exhibit increased expression of IL6 receptor (IL6R), and upon activation by IL6, they induce the expression of vascular endothelial growth factor (VEGF), which drives angiogenesis." (PMID 40427188, 2025). "As well, accumulating studies have shown that IL6R is associated with several tumors, and is involved in tumor angiogenesis, metastasis, and invasion." (PMID 41226525, 2025). "Given the evidence in the literature for differences in the underlying biology of tumours arising in different subsites of the bowel, we investigated if expression of IL6R was different between right-sided or left-sided colon and rectal cases." (PMID 39766336, 2024). "High expression of IL6R in the tumour epithelium was associated with reduced cancer-specific survival in patients with right-sided colon cancer." (PMID 39766336, 2024). "A previous retrospective study of breast cancer reported that high expression of IL6R within tumour cells was associated with reduced cancer-specific survival (n = 593)." (PMID 39766336, 2024). "In a number of in vitro and cell line experiments, targeted inhibition of IL6-Rα abrogated these effects, consistent with a model in which IL-6 is a driver of tumorigenesis in tumor types often associated with PC." (PMID 38689325, 2024). "Next, we aimed to explore underlying differences in right-sided tumours with high IL6R expression between patients who had died of cancer versus those still alive/non-cancer-associated mortalities." (PMID 39766336, 2024). "The IL-6, IL-31, and IL-1RA predictions were primarily associated with tumor extent and smoking history, whereas the soluble receptors (s)-IL-6Rα, s-gp130, and s-IL-33Ra predicted survival even after such adjustments." (PMID 38672565, 2024). "The results showed the tumor response to anti-IL-6R antibody therapy was associated with the IL-6R expression levels in the human CRC xenografts." (PMID 38256960, 2024). "This study aimed to investigate IL6 and IL6R expression in a large cohort of retrospectively collected patient tumour specimens and determine association with clinical outcomes and characteristics." (PMID 39766336, 2024). "IL6R expression within tumour cell membranes and cytoplasm was associated with reduced CSS in the full cohort but statistical significance was lost when TNBC were extracted and analysed." (PMID 37199043, 2023). "In the full cohort Kaplan–Meier survival analysis showed high tumour cell membranous expression of IL6R was associated with reduced CSS (HR = 1.870, 95% CI: 1.264–2.768, log rank p = 0.002)." (PMID 37199043, 2023). "Multiple mechanisms, including inflammatory responses, malignant tumor formation, and epithelial-mesenchymal transition, have been linked to miR-30b through IL-6R signaling pathway." (PMID 36890871, 2023). "In this study, we have developed a model of a bispecific antibody (BS1) targeting two key cell surface receptors, IL-6Rα and IL-8RB, which were recently implicated in a synergistic pathway that drives tumor metastasis." (PMID 38187701, 2023). "In pre-clinical models, combined blockade of PD-L1 and the IL-6 receptor (IL6R) causes synergistic regression of large established tumors and substantially improves anti-tumor CD8+ cytotoxic T lymphocyte (CTL) responses compared with anti-PD-L1 alone." (PMID 36599350, 2023). "They even observed a high level of anti-IL-6R mAb and MDSCs (they inhibit tumour progression) in IL-10-deficient mice." (PMID 34336101, 2021). "CPEB3 can disrupt the crosstalk between cancer cells and tumor-associated macrophages through the IL-6R/STAT3 signaling pathway, and thereby inhibit epithelial-mesenchymal transition." (PMID 34879089, 2021).
tumor (continued). "IL-6 is secreted by various cancer cell types and cancer-associated fibroblasts, causing chronic inflammation in tumours, which then binds IL-6R to form the IL-6/IL-6R complex." (PMID 33855091, 2021). "Conversely, 7 of 25 miRNAs highly associated with IL6R expression were always negatively correlated in at least 5 tumor types, while miR-150-5p was positively correlated in 7 tumors." (PMID 34576335, 2021). "Tumor cells secrete IL-6, which interacts with the IL-6 receptor (IL-6R) on tumor-associated LECs in TME or on LECs in distant organs." (PMID 32630699, 2020). "Here we demonstrate that miR-34a exerted tumor-suppressive effects in HGSC by regulating the IL-6R/STAT3 signaling pathway and the associated expression of Snail, MMP9, CDK4, and survivin." (PMID 31448054, 2019). "MiR155 contributes to impaired T cell-dependent antibody response, promotes production of both monocytic and granulocytic MDSCs and induces chemoresistance through C/EBPβ/IL6/IL6R/STAT3 signaling axis in tumor-associated macrophages." (PMID 30925928, 2019). "Here, important chemoattractants such as Ccl20 and Ccl5 were downregulated in the microarray of IL-6Rα-deficient tumours." (PMID 29695802, 2018). "Detection of markers for αβ T cells and Treg cells in tumours of the obese cohorts revealed a reduction of these cells in IL-6Rα-deficient mice that was largely unaltered when mice received anti-CD25 treatment." (PMID 29695802, 2018). "In contrast, IL-6Rα-deficient tumours had less PCNA immunoreactivity compared with control tumours, whereas tumours from HFD-fed control mice had increased PCNA levels indicative of increased proliferation compared with NCD-fed controls." (PMID 29695802, 2018). "The study revealed a positive association between IL-6R expression, tumour size, and histopathological stage." (PMID 30539028, 2018). "Ultimately, lean control mice developed CAC, whereas γδTCR antibody injection drastically reduced tumour burden in control mice similar to IL-6Rα-deficient mice." (PMID 29695802, 2018). "In line with this evidence, expression of representative IL-6-mediated STAT3 target genes such as Socs3 and Timp1 were largely unaltered in tumor livers of lean IL-6Rα-deficient mice compared to controls." (PMID 30224299, 2018). "We found that peritumoral CD68(+) macrophages were also up-regulated on the seventh week of tumor growth; this change was significantly associated with peritumoral IL-6R (rr = 0.556, P = 0.001)." (PMID 26525581, 2015). "Those with low IL6R expression exhibited less mature myeloid cell infiltration and better overall survival (OS), whereas those with high IL6 levels, high IL6R expression, and high infiltration of tumor-associated CD163+ myeloid cells were associated with poor clinical outcomes." (PMID 40427188, 2025). "Considering that IL-6 can trigger the same effects as FbCM, and given that the IL-6/IL-6R pathway is highly activated in HNSCC tumour, we next investigated whether Fb secreted IL-6 is causing the FbCM-induced EMT and increased radioresistance in HNSCC." (PMID 39858048, 2025). "High expression of IL6R is associated with tumour progression, metastasis and poor prognosis." (PMID 39893643, 2025). "In addition, blocking specific chemokine and cytokine receptors such as CCR2, CCR4 or Il-6R can reduce the recruitment of tumor-associated macrophages (TAMs), myeloid-derived suppressor cells (MDSCs) or regulatory T cells (Tregs)." (PMID 38928238, 2024). "As tumour cells in experimental CRC lose IL-6R expression and become susceptible to IL-6 trans-signalling via the soluble IL-6R,15 our findings underlined that Th9 cells may regulate tumour growth via IL-6 trans-signalling." (PMID 35793807, 2022). "BBR or antibodies to IL-6 and IL-6R may also inhibit STAT3 activation by regulatory media of tumor-associated fibroblasts." (PMID 34885950, 2021).
tumor (continued). "Since MDA-MB-231 and A549 cancer cells lack surface expression of IL-6Rα (unpublished data), it is likely that MH exerts its anti-tumor effect via binding to sIL-6Rα, inhibiting its association with the IL-6 cytokine and ultimately preventing the triggering of the IL-6 trans-signaling pathway." (PMID 31491838, 2019). "Indeed, the qPCR experiments confirmed the reduction of these lymphocyte subsets in IL-6Rα-deficient tumours when compared with controls." (PMID 29695802, 2018). "However, despite the fact that also other cells express Ifnγ and Il17a, the examination of T-cell effector molecules revealed decreased Ifnγ and Il17a expression in obese IL-6Rα-deficient tumours that have been restored upon Treg depletion." (PMID 29695802, 2018). "Furthermore, the association between the pSTAT3 and IL-6R expressions and tumour differentiation, ratio of positive nodes, pathological T stage, and pathological N stage were examined and are reported." (PMID 29890775, 2018). "Moreover, malajusted miR- 155-5p/C/EBPβ/IL6 signaling in tumor-associated macrophage could induce chemoresistance by regulating the IL6R/STAT3/miR-204-5p axis." (PMID 30897064, 2019). "Furthermore, decreased proliferation of IL-6Rα-deficient tumours was confirmed via Ki67 staining." (PMID 29695802, 2018). "Inhibition of the activation of STAT3, e.g. by the anti-IL6R monoclonal antibody Tocilizumab, is known to down-regulate the immune suppression caused by tumor cells, and inhibition of IL-6 signaling may be a therapeutic for patients with cancer when IL-6 is over-expressed." (PMID 30038723, 2018). "However, mice deficient in intestinal IL-6Rα have a similar tumor load compared to control mice." (PMID 30591653, 2018). "Furthermore, STAT3 activation by conditioned medium of tumor-associated fibroblasts could be blocked by berberine or antibodies against IL-6 and IL-6R." (PMID 24380387, 2013). "Recent studies have demonstrated that tumor epithelial cells not only increase IL-6 production in adipocytes but also increase IL-6R levels in myocytes and subsequently sIL-6R levels in plasma, which induce myotube wasting and adipocyte lipolysis." (PMID 41526343, 2026). "Tocilizumab (TCZ), a humanized anti-IL-6R monoclonal antibody that has been clinically approved for autoimmune disorders, exhibits emerging anti-tumor activity across multiple malignancies." (PMID 40733153, 2025). "Preclinical studies using anti-IL-6 or anti-IL-6 receptor (IL-6R) antibodies in tumor-bearing mice demonstrate attenuation of muscle atrophy, adipose tissue loss, and systemic inflammation." (PMID 40704145, 2025). "Peritumoral endothelial cells isolated from HCC patients show greater proliferative capacity in response to IL-6 and soluble IL-6R stimulation compared to endothelial cells from tumor tissue." (PMID 40918452, 2025). "In mouse xenograft models, peritumoral liver tissue exhibits increased microvascular density and elevated expression of proangiogenic genes, including IL-6 and IL-6R, compared to tumor core tissue." (PMID 40918452, 2025). "Activation of IL-6/STAT3, a classic signaling pathway in tumor cells, begins when IL-6 binds to IL-6Rα and gp130 receptor subunits on the membrane surface to form a complex that triggers phosphorylation of JAK kinase and ultimately activation of STAT3." (PMID 41041638, 2025). "The IL‐6 receptor (IL6R) plays a crucial role in various diseases, particularly in the tumour microenvironment and inflammatory responses." (PMID 39893643, 2025). "In the context of the TGFβ vaccine, IL-6R blockade reduced the abundance of tumor-infiltrating T cells and resulted in increased T-cell exhaustion." (PMID 39653766, 2025). "Accumulating evidence has illustrated that the IL-6/IL-6R/STAT3 pathway plays a pivotal role in tumor occurrence and progression; however, the detailed mechanism has not yet been identified." (PMID 40779629, 2025).